MIR3156-1 (microRNA 3156-1)
Synonyms: hsa-mir-3156-1; mir-3156-1
Gene: MicroRNA gene on chromosome 10 (45,164,014 to 45,164,088, forward strand). Ensembl gene ENSG00000263476.
Homologues: Orthologues: chimpanzee MIR3156-1 (100% identical).